IL1B (interleukin 1 beta)
Diseases named in the same sentence as IL1B in open-access papers (continued):
Sharing a sentence is not in itself a finding about the gene and the disease.
cancer (continued). "For instance, Murray & Wynn (2011) demonstrated that IL-1β and IL-6 are robustly upregulated in classically activated macrophages, driving pro-inflammatory responses in infections and cancer." (PMID 40933659, 2025). "IL-1β treatment resulted in the down regulation of Caspase-8 and -3, thus favoring cancer cell proliferation." (PMID 40725140, 2025). "In response to uncontrolled cell proliferation, a neuroinflammatory environment is created—read as elevated levels of IL-1β—which, we elaborate here, favors cancer cell proliferation and spread." (PMID 40725140, 2025). "TNBC cells polarize macrophages toward a mixed M1/M2 phenotype, with TAMs exposed to TNBC-conditioned media expressing significantly higher levels of IL-1β than those exposed to hormone receptor-positive cancer cells." (PMID 40868199, 2025). "KN-62 not only reduces ATP-dependent Ca2+ influx and ethidium bromide uptake but also decreases IL-1β secretion to relieve cancer pain." (PMID 40717979, 2025). "Chronic diseases such as COPD, CHF, CKD, cancer cachexia and aging are often characterized by low‐grade systemic inflammation, with elevated IL‐1β and TNF‐α." (PMID 41292279, 2025). "Pro-inflammatory cytokines IL-1β and TNF-α serve as key inflammatory mediators and have been linked to cancer development in numerous studies." (PMID 40699769, 2025). "Depending on the cancer type, the expression and activity of these enzymes can be influenced by the presence of IL-1β." (PMID 39858071, 2025). "The blockade of IL-1β not only mitigates cancer progression but also provides a protective barrier against cardiovascular complications, which is of vital importance in the current era of SARS-CoV-2 infection." (PMID 40697377, 2025). "IL-1β, extensively studied in the autoinflammatory diseases, contributing to atherosclerosis and cancer progression." (PMID 41333471, 2025). "THGP-treated macrophages showed enhanced phagocytosis of foreign substances and cancer cells, along with increased expression of the IL-1β and TNF-α genes." (PMID 40141094, 2025). "IL-1β contributes significantly to cancer development and progression by promoting uncontrolled cell proliferation, facilitating immune evasion, and supporting metastatic spread." (PMID 40725070, 2025). "Studies conducted over the years have reported an increased expression of IL-1β in the serum of advanced cancer patients compared to samples from healthy donors." (PMID 39858071, 2025). "Stress conditions, such as hypoxic environment, inflammatory signals such as TNFα and IL-1β, or chemotherapeutics additionally enhance its production by cancer cells." (PMID 39201656, 2024). "High IL1β and its receptor expression in cancer cells and CAFs correlate with poor patient survival." (PMID 39766086, 2024). "The IL-1β/IL-1 receptor (IL-1R)/β-catenin pathway increases cancer cell growth and metastasis, leading to higher expression of transcription factors, including SNAIL-1 and c-MYC." (PMID 38990306, 2024). "A co-culture study on lingual squamous cell carcinoma identified that IL-1β released by cancer cells leads to an upregulation of IL-1R and increased activation of IRAK-1 in CAFs." (PMID 39451208, 2024). "CD44 expression on cancer cells was shown to be up-regulated through rhIL-1β treatment, suggesting a positive feedback loop to maintain IL-1β levels." (PMID 39044824, 2024). "IL1β and IL-8 are important pro-angiogenic factors which participate in the growth of cancer cells, play a role in metastasis promotion, and have a pleiotropic effect on immune cells." (PMID 38398148, 2024).
cancer (continued). "In some instances, IL-1β and IL-18 also contribute to the survival of the cancer cells, and that helps them spread to other organs by modulating the epithelial-to-mesenchymal transition (EMT)." (PMID 39769450, 2024). "Despite the assumed value of both the IL-1β and IL-1RA status, only little is known about their (combined) prognostic value and on their correlation to cancer proliferation (Ki-67) and autophagy markers such as AKT." (PMID 38397123, 2024). "Canakinumab, a monoclonal antibody targeting IL1β, demonstrated reduced cancer incidence in the CANTOS trial and reduced incidence and morbidity of lung cancer, spurring interest in its oncology applications." (PMID 39766086, 2024). "We first employed IL-1β, a pleiotropic inflammatory cytokine that was reported to promote mtDNA release in cancer cell line and immune cells." (PMID 38737375, 2024). "The results found that IL-1β expression was significantly elevated in ESCC cancer tissues compared with paracancerous tissues (P < 0.001)." (PMID 38762529, 2024). "In addition, IL-1β infiltrated in the tumor microenvironment promotes tumor growth and metastasis by promoting the expression of IL-1 targets associated with neoangiogenesis as well as soluble mediators in cancer-associated fibroblasts that cause anti-apoptotic signaling." (PMID 38762529, 2024). "Interleukin (IL)-1β, an inflammatory cytokine that can be expressed and produced by the cancer cell itself, has been suggested to promote BC proliferation and progression." (PMID 38254674, 2024). "IL-1β has been shown to drive NET formation through IL-8 or G-CSF production in inflammatory diseases including cancers, but also to directly target epithelial–mesenchymal transition." (PMID 39001538, 2024). "The major pro-inflammatory cytokines include IL-1β, IL-6, and TNF-α, the continuous intensification of inflammation is an important cause of cancer." (PMID 38572238, 2024). "It is known that Il1b and Il6 expression depends on NF-κB activity, and IL-6 plays an important role in the processes of invasive growth and metastasis of malignant tumors." (PMID 39063041, 2024). "IL-1β has been reported in previous studies to exhibit pleiotropic actions on immune cells, angiogenesis, cancer cell proliferation, migration, and metastasis." (PMID 39554609, 2024). "Low concentrations of IL-1β have been shown to stimulate the production of anti-cancer factors and activate the body's inherent immune system against cancer." (PMID 38317229, 2024). "Previous studies have established a correlation between increased IL-1β levels and pathological changes conducive to the development of oral potentially malignant disorders (OPMDs) and cancer." (PMID 39200213, 2024). "The expression of IL1β in triple negative breast cancer (TNBC) has been associated with macrophage-induced immune suppression and cancer progression." (PMID 39353903, 2024). "Cancer cells produce many factors, including IL-1β, CCL2, TGF-β, IL-6, granulocyte-colony stimulating factor (G-CSF) and GM-CSF, which affect innate immune cells, including neutrophils." (PMID 39795864, 2024). "Pseudotime analysis implicates IL1β/CXCL8/CXCR2 axis in the progression of neutrophils from health to cancer and metastasis, with effects on T-cell effector function." (PMID 38358352, 2024). "Joint analysis of IL-1β and CRP levels was characterized by high diagnostic usefulness in predicting the risk of cancer cachexia (AUC = 0.956; p < 0.0001)." (PMID 38610941, 2024). "Several studies reported that IL-1RA induced a restoration of the autophagy process and catabolism reduction in inflammation-altered human cells, while IL-1β acted more like autophagy inhibitor, especially in cancer cells." (PMID 38397123, 2024). "All three proteins, HIF-1α, ANG-2, and IL-1β, are widely studied in the literature as biomarkers of various cancer diseases." (PMID 39275392, 2024).
cancer (continued). "Although IL-1RA was discovered almost concurrently with IL-1α and IL-1β, its value in cancer remains relatively uncertain compared to the other two." (PMID 38339264, 2024). "In a further investigation, simulated microgravity stimulated 3D development of PC-3 cancer cells and differential production of the cytokines IL-1α, and IL-1β, indicating their role in PCa cell growth and progression." (PMID 38745115, 2024). "Conversely, elevated concentrations of IL-1β directly contribute to the proliferation, differentiation, and metastasis of cancer cells to other tissue cells." (PMID 38317229, 2024). "The presence of DCs together with B cells strongly up-regulated IL-10 release, suggesting that DCs control Breg expansion in the presence of cancer cells and that IL-1β plays a key role in reducing IL-10 release." (PMID 39576827, 2024). "Evidence shows that its inhibition or neutralization of IL-1β significantly impacts carcinogenesis and cancer progression." (PMID 39301197, 2024). "The role of IL‐1β in modulation of EMT markers (E‐cadherin and snail) has been studied earlier, indicating that IL‐1β enhanced snail expression led to increased metastatic burden in the H&N cancer cell line model." (PMID 38686626, 2024). "The excess amount of IL-1B promotes an environment conducive to cancer development by enhancing uncontrolled cellular proliferation and differentiation while interfering with apoptosis." (PMID 38858637, 2024). "IL-1β, by inflammasome activation, is critical also to produce IL-22 by T helper 22 (Th22) cells, a cancer-promoting cytokine directly induced by some cancer cells." (PMID 38334625, 2024). "According to previous reports, IL‐1β rs16944 AA genotype was found in approximately about 15%–22% in healthy individuals and 18%–22% in patients with cancer." (PMID 38798075, 2024). "Following treatment with 5-azacytidine, we found that the PTX3 transcripts were restored in cancer cells but IL-1β and TNF-α exerts a different effect on the induction of PTX3 gene in a cell type-specific manner." (PMID 38243273, 2024). "Cancer stool samples showed increased levels of IL1B, IL8, and PTGS2 transcripts compared to polyp and control groups." (PMID 39523395, 2024). "Debates to use or not to utilize IL-1β inhibitors in cancer treatment have risen because anti-cancer medicines can also stimulate the synthesis of IL-1β by immune or cancer cells, with differing consequences on the progression of cancer." (PMID 39554609, 2024). "Recently, IL‐1β has been reported to mediate HCC progression by promoting epithelial–mesenchymal transition (EMT) in cancer cells." (PMID 38798075, 2024). "IL1 signalling in relation to inflammation in cancer has been extensively studied and consequently, IL1B blockers and the receptor antagonist IL1RA are of clinical interest." (PMID 39728924, 2024). "NLRP3 inflammasome activation leads to the processing and secretion of the pro-inflammatory cytokines IL-1β and IL-18, and polymorphisms or mutations in NLRP3 have been linked to different types of cancer." (PMID 38334625, 2024). "The expression of blood-borne B2MG, a biomarker for cancer and many inflammatory diseases has been found positively correlated with age, the levels of p16ink4a, IL-1β and IL-6, and the oxidative stress." (PMID 38447216, 2024). "The process impacts the proliferation, invasion, and metastasis of cancer cells and is triggered by inflammasomes, gasdermin D cleavage, and elevated IL-18 and IL-1β cytokine production." (PMID 39220125, 2024). "SP1 is associated with immunosuppression in several cancer types, including TNBC, and IL-1β is responsible for the activation of a pro-inflammatory pathway." (PMID 39576827, 2024). "Compared with the IL-1R ligand IL-1β, less is known on the role of IL-1α-dependent proinflammation in cancer despite it has become an apical regulator of inflammatory response in a much wider cellular scenario due to its unique properties (71, –, 73)." (PMID 38117084, 2024).
cancer (continued). "Collectively, these studies describe the involvement of IRAK1 in the activation of downstream pathways, including NF-κB and MAPKs/NLRP3/IL-1β, which promote the production of mesenchymal markers that induce a shift in the cellular phenotype of cancer cells." (PMID 39451208, 2024). "HT29 cells exposed for 24 h to 10 ng/mL IL1β showed an increased production of ROS, but when cancer cells were pretreated with SW, CW, and BF there was a significant reduction in ROS production that reached levels lower than baseline conditions." (PMID 39125413, 2024). "Although IL-1β expression in the TME is related to cancer progression, DCs expressing IL-1β are more immunogenic, and reduce the expansion of immune-suppressive cells." (PMID 39576827, 2024). "It is important to highlight that IL-1β, IL-6, IL-8, and TNF-α are directly implicated in cancer development/progression." (PMID 38612423, 2024). "This activation is associated with increased production of IL-1β and has also been associated with the EMT process and cancer progression." (PMID 38486106, 2024). "The inhibition of IL-1β interaction with its receptor was observed to maintain the disseminated cancer cells in the bone microenvironment in a state of dormancy." (PMID 39201656, 2024). "For IL-1β, Rébé and Ghiringhelli described that this cytokine has pleiotropic effects on immune cells, angiogenesis, cancer cell proliferation, migration, and metastasis." (PMID 39451257, 2024). "Several cytokines, including leptin, IL-1B, IL-6, IL-8, IL-23, IL-17, and IL-10, stimulate cancer progression, while others, including IL-2, IL-12, and IFN-γ, inhibit cancer proliferation and/or invasion." (PMID 37979099, 2024). "We first measured the expression of genes involved in adipocyte differentiation (PPAR-γ, AP2, HSL, Adiponectin, Leptin), cancer-associated fibroblast (CAF) markers (LIF, FAP, α-SMA), and inflammation (IL-6, IL-8, IL-1β, CXCL-10, TNF-α)." (PMID 39072314, 2024). "Third, no cytokines were statistically significantly associated with cancer risk or subtypes after Bonferroni correction, including six inflammatory factors with suggestive correlations - Eotaxin, SCF, IL-1β, VEGF, IL-18, and IP-10." (PMID 38957317, 2024). "IFN-γ released by macrophages triggers Toll-like receptor activation and induces cell cycle arrest in cancer cells, while IL-1β acts as a significant driver of inflammation." (PMID 39474419, 2024). "A number of studies have determined the important role of IL-1β in the occurrence and development of malignant tumors." (PMID 38397123, 2024). "This suggests that IL-1β induces cancer cell migration and invasion via the PAK1 pathway, downstream of ERK, p38, and NF-κB signaling." (PMID 38188678, 2023). "Although overwhelming evidence supports a role for IL-1β in promoting oncogenesis, the role of IL-1β in established cancers is less clear." (PMID 37461742, 2023). "TAMs secrete several cytokines, including interleukin (IL)-1β, which participate in cancer migration and invasion." (PMID 38188678, 2023). "In balder cancer, IL-1β induces expression of aldo–keto reductase 1C1 (AKR1C1), which is associated with invasion, cisplatin resistance, and metastasis of cancer cells." (PMID 36932407, 2023). "Once IL1β binds to its receptor IL-1R1, downstream signalling leads to the activation of NF-kB dependent genes, which in turn can promote cancer growth." (PMID 37065483, 2023). "In cancer, the expression of inflammatory signals, such as TNFα, IL-1β, and IL-6, are crucial indicators of sensitivity to chemotherapy and patient survival." (PMID 36672449, 2023). "Clinically, IL-1β, IL-18, IL-6, and MIC-1/GDF-15 levels are associated with the risk of carcinoma and the prognosis of established cancer." (PMID 37715239, 2023). "Previous studies have indicated that the activation of NLRP3 inflammasome can contribute to cancer progression by releasing inflammatory cytokines such as IL-1β and IL-18." (PMID 38026959, 2023).
cancer (continued). "Increases in adipose tissue volume and macrophage influx result in higher levels of fever-inducing proinflammatory cytokines (TNF-α, IL-1β, and IL-6), already increased as a consequence of cancer." (PMID 37374212, 2023). "Several reviews of the literature have reported the involvement of various biochemicals such as β-endorphins, IL-1β, dynorphines, substance P in the inhibition of cancer pain by acupuncture or electroacupuncture in animal models of inflammatory pain." (PMID 37832094, 2023). "Accordingly, supernatant secreted from MDSCs induces a surge of receptor expression for IL-6, IL-10 and IL-1β in cancer cells." (PMID 38304256, 2023). "Recently, it has been reviewed that IL6, TNFα, and IL1β play a central role in the toxicities of cancer immunotherapies." (PMID 36875156, 2023). "The IL-1 family includes IL-1β, which induces cancer migration and invasion, promotes cancer growth and metastasis, and is secreted by TAMs, fibroblasts, immune cells, and cancer cells." (PMID 38188678, 2023). "For instance, NLRP1 (−/−) mice exhibit increased inflammation and cancer burden when IL‐1β levels are low." (PMID 37752941, 2023). "Since the readout activity of NLRP3 is the release of mature inflammatory cytokines, we will focus in the next section on the role of IL-1β and IL-18 in cancer progression." (PMID 37298187, 2023). "In OSCC, IL1β is involved in the invasion and migration of cancer cells, while OSCC cells were reported to induce stromal cells to produce IL6, facilitating bone invasion by osteoclast formation." (PMID 36900301, 2023). "Previous studies have established that both IL-1β and IL-18 play essential roles in fostering cancer cell metastasis." (PMID 38066523, 2023). "As to acupuncture analgesia, inflammatory pain animal models actually reported that many bioactive chemicals (such as β-endorphins, IL-1β, dynorphines, substance P) were involved in acupuncture inhibition of cancer pain." (PMID 36950556, 2023). "The pro-inflammatory cytokines IL-1β, IL-6, and IL-8 were two-fold elevated in contrast to TNFα, which appears to be a cytokine discriminating the inflammatory response in aging and cancer." (PMID 38003396, 2023). "Pyroptosis activation can lead to the release of IL-1 and IL-1β, which can promote cancer development in several ways." (PMID 37061535, 2023). "Further analysis of genes dysregulated in cancer associated neutrophils revealed that TNF-α, Oncostatin M (OSM), IL-1β and IL-6 cytokines are expressed in the neutrophils with corresponding expression of their receptors in CTCs." (PMID 37006265, 2023). "The MAPK and NF-κB signaling pathways are known to induce IL-1β expression, which in turn promotes cancer cell migration and invasion." (PMID 38188678, 2023). "Genes related to the cancer-associated adipocytes (CAA) phenotype were found induced, and these included the C–C motif chemokine ligand 2 (CCL2), interleukin-1 beta (IL-1B), and C-X-C motif chemokine ligand 8 (CXCL8)." (PMID 37833751, 2023). "Recombinant IL-1β was infused intravenously over 30 min into 19 human cancer patients at several doses that produced calculated serum concentrations between 50–2,550 pg./mL." (PMID 37928695, 2023). "Together, these results demonstrate that PIK-93 enhances the antitumor effect of M1 macrophages on cancer cells by directly activating the IL-1β signaling pathway in M1 macrophages." (PMID 37027467, 2023). "exATP release drives DC recruitment and activation by P2RX7 ligation, generating adaptive immunity against cancer by tumor-derived antigens and IL-1β secretion." (PMID 36741002, 2023). "In that case, the combination usage of ADT and anti‐IL‐1β antibody would be a plausible therapeutic approach in a broader range of ADT responsive cancers." (PMID 37092583, 2023). "For example, IL-6, IL-1β, and TNF-α were increased at cancer early stage and associated with disease severity." (PMID 36899319, 2023).